PLEKHD1 (pleckstrin homology and coiled-coil domain containing D1)
Synonyms: UPF0639
Tractability: PROTAC: ubiquitination databases record sites on it.
Gene: Protein-coding gene on chromosome 14 (69,484,692 to 69,531,551, forward strand). Ensembl gene ENSG00000175985.
Genetic constraint (gnomAD): Loss-of-function variants: 52 observed, 71.89 expected, observed/expected ratio (o/e) 0.72, 90% interval 0.58 to 0.91. The upper end of that interval is the gene's LOEUF score, 0.91, which puts it in group 3 of 6, group 1 being the genes least tolerant of losing a copy. Missense variants: 584 observed, 666.65 expected, observed/expected ratio (o/e) 0.88, 90% interval 0.82 to 0.94. Synonymous variants: 236 observed, 252.96 expected, observed/expected ratio (o/e) 0.93, 90% interval 0.84 to 1.04.
Homologues: Orthologues: chimpanzee PLEKHD1 (99% identical), macaque PLEKHD1 (99% identical), dog PLEKHD1 (98% identical), pig PLEKHD1 (98% identical), mouse Plekhd1 (95% identical), guinea pig PLEKHD1 (95% identical), rat Plekhd1 (94% identical), rabbit PLEKHD1 (84% identical), tropical clawed frog plekhd1 (67% identical), zebrafish plekhd1 (57% identical), Caenorhabditis elegans F31D4.5 (31% identical). Paralogues in human: DEF6 (21% identical), SWAP70 (20% identical).
Diseases named in the same sentence as PLEKHD1 in open-access papers:
PLEKHD1 is named in the same sentence as 2 diseases in open-access papers, as found by Europe PMC text mining. Sharing a sentence is not in itself a finding about the gene and the disease.
PLEKHD1 shares sentences with these, for which no sentence is quoted: cancer (1 paper); neuroblastoma (1).